CD4 (CD4 molecule)
Diseases named in the same sentence as CD4 in open-access papers (continued):
Sharing a sentence is not in itself a finding about the gene and the disease.
uveitis (continued). "However, MC5R is reported to protect from uveitis-derived retinal damage by regulating the activation of CD4+ regulatory T cells and to attenuate retinal degeneration in an experimental model of diabetic retinopathy." (PMID 37359372, 2023). "Nevertheless, a clear picture of the regulation of CD4+ T cells and B cells and the changes associated with the progression of uveitis is lacking." (PMID 36195600, 2022). "Importantly, the upregulation of PIM1 in CD4+ T cells and plasma cells is conserved in a human uveitis, Vogt-Koyanagi-Harada disease (VKH), and inhibition of PIM1 reduces CD4+ T and B cell expansion." (PMID 36195600, 2022). "Uveitis was evaluated by clinical and histopathological scoring, and comparisons were made in WT vs. Nlrp12−/− mice, lymphopenic Rag1−/− mice reconstituted with WT vs. Nlrp12−/− CD4+ T cells, or among bone marrow (BM) chimeric mice." (PMID 35313917, 2022). "Moreover, another study represented higher CD8+ TSCM cells in patients with AA and uveitis as well as higher CD4+ TSCM proportions in SLE patients." (PMID 36169248, 2022). "Furthermore, our study verifies the upregulation of PIM1 in CD4+ T cells and PCs in a human uveitis, Vogt-Koyanagi-Harada disease (VKH)." (PMID 36195600, 2022). "An increase in CD4+ CD161+ non-classical Th1 cells or Th17/Th1 cells in the bloods from patients with juvenile idiopathic arthritis (JIA)-associated uveitis as compared with idiopathic anterior uveitis patients and healthy controls has been reported." (PMID 34502490, 2021). "In addition, Th17/Th1 cells (CD4+IL-17+CD161+) have been demonstrated to be sensitive to methotrexate (MTX) treatment in JIA uveitis." (PMID 34502490, 2021). "In this review, we have investigated the evidence as to whether these ‘plastic CD4+ T cells’ are functionally active in uveitis." (PMID 34502490, 2021). "The RIII background has been shown to expand the peripheral population of uveitis-relevant CD4+ T cells that appear in the intestinal lamina propria (LP) as early as 17 days of age, and uveitis has been shown to have 100% penetrance in these mice by 2 months of age." (PMID 34746029, 2021). "Importantly, the exacerbated uveitis observed in Nod2−/− mice was CD4+ T cell-dependent, as depletion of CD4+ T cells ameliorated uveitis in both Nod2−/− mice and WT mice." (PMID 33106495, 2020). "Nod2-deficient CD4+ T cells produce more IL-17 and cause worse uveitis; a mechanism that is independent of Rip2-signaling or microbial stimuli, as MDP or in adjuvant." (PMID 33106495, 2020). "However, Th1-type CD4+ T cells from uveitis patients with VKH disease or Behçet’s disease highly expressed PD-1 on their surfaces." (PMID 32899567, 2020). "CD4+ T cells purified from naïve R161M mice or Nod2−/−R161M mice were transferred into naïve syngeneic B10.RIII Rag2−/− mice that were monitored for development of uveitis." (PMID 33106495, 2020). "In addition, the infiltration of pathological CD4+ T cells, especially Th17 and Th1, into the retina is involved in the pathogenesis of uveitis." (PMID 33281814, 2020). "CD4+ T cells mediate systemic and local inflammation in uveitis." (PMID 31475011, 2019). "Interestingly, a high expression of ICOS on CD4+ T cells has been described in BD patients with active uveitis, suggesting a role in the pathogenesis of uveitis, possibly through upregulation of IFN-g, IL-17, and TNF." (PMID 29850627, 2018). "However, TLR2 and TLR9 stimulation showed lower proliferation of CD4+ Teff cells in non-uveitis TB patients, hinting towards the possible role of mycobacterial factors as immune modulators in patients with IOTB as well." (PMID 30218032, 2018). "However, they can be detected early in the disease prodrome and in the B10.RIII uveitis model peak at the same time as CD4+ IL-17 expression." (PMID 29530739, 2018).
uveitis (continued). "The increase of IL-2 in BD patients with active uveitis and the decrease in BD cases without uveitis and recovered BD uveitis could be evidence for the role of CD4+T helper cells in patients with uveitis." (PMID 28468317, 2017). "Also, a trend between lower CD4 cell counts and uveitis was observed among those with HIV infection [median of 226 (IQR 137–332) cells/mm3 for keratouveitis vs. 343 (IQR 194–427) cells/mm3 for keratitis, p = 0.09]." (PMID 27236644, 2016). "IL-22 producing CD4+ cells have been reported to play a role in BD patients with active uveitis." (PMID 25061613, 2014). "TNF-α exerts its proinflammatory effects by activating macrophages, facilitating CD4+ T cell development, and upregulating other cytokines, and its levels have been shown to be elevated in the serum and ocular fluid of uveitis patients, especially during the active phase." (PMID 25061613, 2014). "Moreover, studies that characterized the VZV-specific T cell response in patients with VZV-induced uveitis revealed that CD4 T cells were responsible for the bulk of the T cell response." (PMID 22102814, 2011). "The high TNF-α levels observed in the serum of our IU patients are in accord with earlier findings of high expression of TNF-α by peripheral blood CD4+ lymphocytes in patients with active uveitis of different origins, in active Behçet disease and in presumed ocular sarcoidosis." (PMID 21850175, 2011). "Hypoxia-inducible factor 1 alpha (Hif1α) is confirmed as an up-regulated EAU-associated differentially expressed gene (DEG) in Th1, Th17, and Treg cells, and enhanced Hif1α expression in CD4+ T cells was conserved and may promote their proliferation in uveitis patients." (PMID 40867565, 2025). "Importantly, these memory CD4+ T cells demonstrate prolonged survivability and critical uveitogenicity, supporting their important functions in sustaining a protracted course of intraocular inflammation in uveitis." (PMID 40323267, 2025). "Moreover, long-lived T cells appear to drive chronicity: bone marrow–resident memory CD4+ T cells have been shown to sustain inflammation in experimental uveitis, which may explain relapsing disease courses." (PMID 41394857, 2025). "Based on our observation that CD4+ T cells were expanded within uveitic eyes of Nlrp12−/− vs. WT mice, we evaluated whether Nlrp12 might inherently control T cells in mitigating uveitis." (PMID 35313917, 2022). "However, little is known about the involvement of so-called plastic CD4+ T cell subsets in uveitis." (PMID 34502490, 2021). "However, Th1-type CD4+ T cells from the uveitis patient greatly expressed TLT-2 on their surfaces." (PMID 32899567, 2020). "In addition, iPS-RPE cells activated uveitis CD4+ T cells through the B7-H3-TLT-2 receptor." (PMID 32899567, 2020). "The important relevance of these studies to uveitis is that re-programming under chronic inflammation remains a dynamic process at late stages of disease, with recirculation of CD4+ cells, changes in the composition of infiltrating immune cells and changes in their rates of recirculation." (PMID 29530739, 2018). "However, we observed a relatively large uveitis-subtype specific difference in memory CD4 (TM) cell proportion, which suggests that the involvement of T helper populations might be different between uveitis subtypes." (PMID 30429855, 2018). "Thus, CD4 cells mediate whereas CD8 cells suppress the development of uveitis." (PMID 22482083, 2012). "Indeed, recent data indicate that IFN-α treatment causes significant increases in CCR5 mRNA expression in PBMC cultures from both HIV-infected and uninfected individuals, and IFN-α treatment of patients with uveitis resulted in increases of CCR5 expression on peripheral blood CD4+ T cells." (PMID 20174557, 2010). "Among all taxa in HuFl mice, Akkermansia abundance was shown to be a prominent correlate of severe uveitis and IFN-γ-producing CD4+ T cells in the gut, whereas SCFA-producing Firmicutes were reduced in the same animals." (PMID 41509494, 2025).
uveitis (continued). "BD uveitis shows significant myeloid cell infiltration and CD8+ T cell clonality with cytotoxic phenotype, while VKHD uveitis is dominated by CD4+ T cells with Th1-like phenotype." (PMID 40867565, 2025). "Elevated levels have been observed in aqueous humor of uveitis patients and in experimental autoimmune uveitis (EAU) models, where it contributes to CD4+ T cell recruitment and tissue damage." (PMID 40718791, 2025). "Our study found that CD3 on CM CD4+ T cells and CD3 on CD45RA- CD4+ T cells interacted with uveitis, thus CD3 on CM CD4+ T cells and CD3 on CD45RA- CD4+ T cells play a pivotal role in the development of uveitis." (PMID 39144656, 2024). "When patients with HIV present with uveitis-related changes, a complete systematic assessment should be started, including the duration and treatment of HIV, CD4+ T cell count, HIV viral loads, and serological tests." (PMID 36851658, 2023). "Since CD4+ T cells are the major players in HAU, ERU and the induced uveitis models, we subsequently focused on the metabolic phenotype of this specific cell subset." (PMID 34385998, 2021). "Lymphocyte population (CD4+ and CD8+ T cells and CD19+ B cells) infiltrating the vitreous also varied with uveitis etiologies." (PMID 34054864, 2021). "To further investigate the impact of A20 on CD4+T cells in the development of uveitis, we investigated the expression of A20, IL-17, and IFN-γ in CD4+T cells from active BD patients." (PMID 33613524, 2020). "Interestingly, iPS-RPE cells could also stimulate CD4+ T cells from uveitis patients." (PMID 32899567, 2020). "In our study, the frequency of CD4+CD25+Foxp3+ Treg cells and the expression of Foxp3 mRNA were significantly decrease in AAU, which was consistent with previous studies in human uveitis." (PMID 28091550, 2017). "We have further purified the autoreactive CD4+ TL from these P2Y2-/- or P2Y2+/+ immunized mice and have tested their capability to induce uveitis by adoptive transfer into naïve C57Bl/6 mice." (PMID 25692550, 2015). "In patients with uveitis, GITR was found to be an activation marker for CD4+ T cells and was co-expressed with CD25 on CD4+ T cells in peripheral blood." (PMID 23514269, 2013). "Consistent with the role of Th17 in etiology of uveitis, mice with targeted deletion of STAT3 in the CD4+ T cell compartment (CD4-STAT3KO) are resistant to development of EAU." (PMID 22238646, 2012). "Moreover, we validated the upregulation of DGAT1 in CD4+ T cells from patients with Vogt-Koyanagi-Harada (VKH) disease, a human uveitis." (PMID 40197365, 2025). "As uveitis is more related to CD4+ T cells and there were no significant variations in the percentages of other immune cell types in EAU mice, we were not going to further investigate in this paper." (PMID 39823532, 2025). "In addition, human uveitis, Vogt−Koyanagi−Harada disease (VKH), is characterized by the overexpression of PIM1 in CD4+ T cells and plasma cells, and PIM1 inhibition decreases the expansion of CD4+ T and B cells." (PMID 39372407, 2024). "IL-27p28 transgenic mice immunized with IRBP did not develop significant uveitis, showing low disease scores, few percentages of CD4+IL-17A+ and CD4+IFNγ+ T cells in the eyes, and reduced CD4+GM-CSF+ T cells in the ocular cell infiltrate." (PMID 38566992, 2024). "Paired TCRα and TCRβ V(D)J sequences were obtained from P2 tetramer-binding CD4 T cells from the eye-draining lymph nodes of mice with or without uveitis." (PMID 38261611, 2024). "There were 338 distinct TCR clonotypes out of 380 TCR in P2-binding (P2+CD4+) T cells from the LN of AireGW/+Lyn−/− mice without uveitis." (PMID 38261611, 2024). "CMV retinitis and uveitis were the most prevalent ocular manifestations in both patient groups, regardless of their CD4+ T-cell counts (above or below 100), indicating a similarity in the spectrum of ophthalmic manifestations between the two groups." (PMID 38133300, 2023).
uveitis (continued). "Conversely, VKHD uveitis but not BD uveitis showed an overwhelming dominance by CD4+ T cells (> 80%) within the T cell population due to expansion of CD4+ T cell clusters with effector memory (Tem) phenotypes." (PMID 37720629, 2023). "A recent immunohistochemical study conducted on iridectomy specimens from patients with JIA uveitis revealed plasma cells to be abundant, while CD4+ and CD8+ cells were not always detectable, even if a modest predominance of the former was observed." (PMID 36009588, 2022). "Control Rag1−/− mice lacking CD4+ T cells did not develop uveitis after immunization, confirming the requirement for CD4+ T cells in this model." (PMID 33106495, 2020). "Finally, experiments in an experimental model of uveitis proved that local A20 overexpression plays a protective role in EAU which coincides with the maintenance of BRB integrity and inhibition of CD4+T cell activation." (PMID 33613524, 2020). "The number of PD-1+FoxP3+CD25+CD4+ Tregs trended higher in the uveitis cohort under resting conditions, but was not statistically significant." (PMID 31729418, 2019). "Stimulation of A2Ar stimulation had some enhancement of the PD-1+FoxP3+CD25+CD4+ subset in healthy controls and uveitis patients but was not significantly different between the two groups." (PMID 31729418, 2019). "Similar to AAU patients, IAU patients displayed an elevated frequency of CD4+ IL-10+ T cells in comparison with HC, regardless of uveitis activity, and increased IL-4 expression during uveitis inactivity." (PMID 30105034, 2018). "In summary, our data show that CD4+ T-cells in chronic relapsing, remitting sight-threatening non-infectious uveitis deviate toward the Th1 type and that Treg with upregulated levels of T-bet and TIGIT expression are associated with disease remission." (PMID 29774027, 2018). "Finally, we observed a significant decrease in CD4+ Tm CD27+CXCR5+ cells (i.e., follicular T helper cells) in uveitis patients." (PMID 30429855, 2018). "In contrast to AAU patients, the frequency of CD4+ IL-17+ T cells was significantly enhanced in IAU patients during active uveitis while the expression of IFN-γ by CD4+ T cells was not altered in IAU patients." (PMID 30105034, 2018). "In this model, wild-type MCMV, lacking HEL, did not induce overt uveitis, suggesting that disease is mediated by antigen-specific peripherally activated CD4+ T cells that infiltrate the retina." (PMID 29079770, 2017). "Higher frequencies of FoxP3+, CD4+ Tregs were found in intestinal lymphoid tissues (cecal and colonic LPL) in SCFA-treated EAU mice than in the EAU control mice at 1 week post-immunization, prior to the onset of uveitis (NaCl 1w: 59.9 ± 5.6%vs." (PMID 28924192, 2017). "Adoptively transferred naïve HEL-specific CD4+ T cells proliferated in the eye draining lymph nodes, but did not induce uveitis." (PMID 29079770, 2017). "The role of CD4+ and CD8+ lymphocytes in uveitis may therefore go well beyond the initiation of tissue destruction, and include the regulation of immunosurveillance of the local microenvironment by controlling the flow of cells in and out of the tissue." (PMID 24858699, 2014). "BD patients with active uveitis showed a significantly higher expression of IL-22 in the supernatants of stimulated PBMCs and CD4+T cells compared with BD patients without active uveitis and normal controls." (PMID 23527071, 2013). "CD4/CD8 ratio higher than 4.0 has been reported to have positive predictive value of 70% in patients having noninfectious uveitis." (PMID 24282811, 2013). "In addition, administration of monoclonal antibody against CD8 or CD4 revealed that, whereas monoclonal antibody against CD8 enhanced uveitis, against CD4 suppressed uveitis." (PMID 22482083, 2012).
uveitis (continued). "Further analysis indicated that SOCS3 promotes the expansion of Th17/IFN-γ CD4 T cell populations, implicating SOCS3 in the progression of severe uveitis and framing it as a potential target for medicinal chemistry campaigns targeting uveitis and other autoimmune diseases." (PMID 39676878, 2024). "In addition, iPS-RPE cells failed to suppress PD-1-siRNA-transfected T cells from CD4-positive uveitis T cells in vitro." (PMID 32899567, 2020). "We were rigorous in our clinical phenotyping of the recruited subjects and undertook a comprehensive immunophenotypic analysis of CD4+ T-cells derived from these groups, including functional and epigenetic methylation studies, which has not been previously performed in uveitis patients." (PMID 29774027, 2018). "The results showed that the frequency of IL-22/IL-17 double positive CD4+T cells from BD patients with active uveitis (0.86%±0.27%) was significantly higher than in BD patients without active uveitis (0.40%±0.13%, p<0.001) or normal controls (0.43%±0.15%, p = 0.001)." (PMID 23527071, 2013). "However, only a part of the IL-22-positive CD4+T cells was also positive for IL-17 in BD patients with active uveitis or without active uveitis and normal controls (31%–41%)." (PMID 23527071, 2013). "Furthermore, the frequency of IL-22 positive CD4+ T cells from BD patients with active uveitis (2.8%±1.14%) was significantly higher than from BD patients without active uveitis (0.97%±0.44%, p = 0.002) or normal controls (1.23%±0.51%, p = 0.005)." (PMID 23527071, 2013). "In R161M mice, the CD4+ T cells recognize IRBP via a transgenic αβ TCR and develop spontaneous uveitis without immunization." (PMID 33106495, 2020). "The flow cytometric analysis of AAU and IAU patient samples with active or inactive uveitis and HC showed an unaltered frequency of peripheral CD3+ CD4+ T cells (data not shown)." (PMID 30105034, 2018).